CXCL1 (C-X-C motif chemokine ligand 1)
Diseases named in the same sentence as CXCL1 in open-access papers (continued):
Sharing a sentence is not in itself a finding about the gene and the disease.
infection (continued). "Growth factors and chemokines that support myeloid cell influx and expansion after infection, including M-CSF, G-CSF, MCP-1 (CCL2), MIP-1α (CCL3), MIP-1β (CCL4), KC (CXCL1) and MIP-2 (CXCL2), are also highly abundant in S. aureus infected femurs relative to mock infected femurs." (PMID 30978245, 2019). "These striking differences in fungal burdens were recently found to be due to candidalysin-dependent induction of IL-1β and CXCL1 secretion from CARD9+ microglial cells, which function to recruit CXCR2-expressing neutrophils to the brain to control the infection and hence reduce fungal burdens." (PMID 31401652, 2019). "Among them, Cxcl1, Cxcl2, Cxcl3, Cxcl10, IL1b, Socs3, and Mmp14 were overexpressed more than 100-fold compared with the non-infected sample regardless of infection type." (PMID 30858471, 2019). "Given that L. major pre-infection of BMDM prior to LPS stimulation did not affect CXCL1 production, we posited that L. major regulates secreted CXCL1 in the extracellular milieu." (PMID 31260451, 2019). "CXCL1 and CXCL2 recruit neutrophils and other leukocytes to sites of infection and inflammation." (PMID 31848276, 2019). "Melatonin treatment (30 nM) reduced the levels of IL-6 (2-fold), MCP-1/CCL2 (5-fold), and RANTES/CCL5 (6-fold) compared to vehicle treatment after both 4 and 24 h of infection, while both vehicle and melatonin treatment reduced the levels of IL-10, MIP-2/CXCL2, and KC/CXCL1." (PMID 30949455, 2019). "In addition, macrophage depletion led to reduced production of CXCL1, and CCL4 24 hours after infection." (PMID 30102746, 2018). "Furthermore, plasma levels of inflammatory mediators interleukin-6 (IL-6), CXCL-1, and tumor necrosis factor (TNF) were significantly lower in C5ar1−/− mice than in WT mice at 12 h of infection." (PMID 29362231, 2018). "While the ST1 strain P1/7 and the ST25 strain 89-1591 both induced a variety of cytokines following infection of murine DCs (TNF, IL-6, IL-12p70, and CXCL1), only levels of IL-6 and CXCL1 induced by P1/7 (ST1) were significantly higher than those induced by 89–1591 (ST25) (p < 0.01)." (PMID 30001363, 2018). "Regarding the chemokines, diverse studies in humans and mice have indicated that CXCL1, CXCL9, CXCL10, CCL2, CCL3, CCL4, and CCL5 are important in controlling the infection during the acute phase, and the levels of virtually all of them were increased in both BALB/c and C57BL/6 mice." (PMID 29662478, 2018). "Chemokines, used to attract leukocytes to sites of infection, were also produced by ZIKV-infected Sertoli cells and RANTES (CCL5), fractalkine (CX3CL1), IP-10 (CXCL10) and GRO (growth related oncogene CXCL1) were found in the supernatant after 46 h of inoculation." (PMID 29751638, 2018). "CXCL1, CCL2, and CCL7 in the lungs were significantly increased in aged mice after infection." (PMID 30018181, 2018). "Elevated CXCL1 expression was not surprising, considering its chemoattractant properties and the neutrophil burden observed in the posterior segment following infection." (PMID 29661181, 2018). "We report a strong induction of numerous pro-inflammatory cytokines, chemokines and AMPs such as CXCL1, CXCL2, CXCL5, CXCL8, CCL20, TNFα, TSLP, IL-23α, IL-32, IL-6, hBD2 and S100A7 during the infection of monolayered primary keratinocytes and reconstructed epidermis with the wild-type PAK strain." (PMID 30070169, 2018). "At lower infection doses, significant differences in height and kinetics of cytokine concentrations in BAL-f were mostly confined to the time point around the maximum cytokine response (2–4 h for IL-1β and Ccl3, 2–8 h for TNF, 8–24 h for Cxcl-1, Ccl2)." (PMID 29734720, 2018). "Infection of alveolar Mφ by virulent M. bovis induced greater transcription of several chemokines, e.g., chemokine (C-C motif) ligand 5 (CCL5) and chemokine (C-X-C motif) ligand 1 (CXCL1), than that induced by an attenuated isogenic strain." (PMID 29263113, 2018).
infection (continued). "As one of the most crucial proinflammatory cytokines, IL-17A plays an important role in host defense against pathogen infection by stimulating cytokines (TNF-α, GM-CSF, etc) and chemokines (CXCL1, CXCL2, IL-8, etc) expression leading to neutrophil expansion and chemotaxis." (PMID 28035060, 2017). "Consistent with greater neutrophil numbers, mice infected with virus expressing NS1-wt exhibited 7.5-fold and 15-fold greater CXCL1 and CXCL2 gene expression, respectively, in their lungs compared with mice infected with virus expressing NS1-Y84F on day 1 post-infection." (PMID 28498306, 2017). "Upon infection of Il13−/− and WT mice with S. pneumoniae, we observed a more pronounced early (6 hr) influx of neutrophils in bronchoalveolar lavage fluid (BALF) and lung and enhanced amounts of lung CXCL1 in Il13−/− mice." (PMID 28228256, 2017). "Unimpaired expression of CXCL1, 5, and 10 chemokines in IL-17 KO mice seems to compensate for early neutrophil influx but not for later stages of infection where the pulmonary neutrophil response was decreased in KO animals." (PMID 29184554, 2017). "In our analysis, we observe that a subset of these cytokines reported to be present in the serum also show transcriptional upregulations in PBMCs by 4 days post-infection (IL6, IL1B, IL1RN, CCL8, CXCL10) and by 7 days post-infection (CCL2, CCL3, CSF1, TNF, CXCL1, FAS and CXCL8)." (PMID 27595844, 2016). "In addition, the levels of CXCL1/KC and CXCL10/IP-10 in BALF from Mint3−/− mice remained lower than those from WT mice on day 8 after infection." (PMID 27883071, 2016). "As hypothesized, the levels of inflammatory mediators (IL-6, CCL2, CCL3, CXCL1, CXCL10 and IFNα as expected) were lower in the blood and the spleen of Ifnar1-/- mice compared to WT counterparts at all times post-infection, except for IFNγ." (PMID 27792766, 2016). "Within this group, IFNα, CCL4, CXCL1, and CXCL10 were upregulated following ArmΔGPC priming but prior to infection with Cl13, suggesting that these cytokines were upregulated not only upon Clone 13 infection but also by the priming agent." (PMID 25569216, 2015). "The concentrations of all cytokines and chemokines in the spleen 20 hours after infection (IL-6, IL-10, CXCL1, and CXCL2) were not different among all three groups studied." (PMID 25563481, 2015). "The mRNA level of neutrophil attracting CXCL1/2 was slightly but not significantly elevated following infection." (PMID 25993659, 2015). "Using cells only treated with IL-33 or cells only infected with HTNV as controls, the mRNA expression of IL-1β, IL-6, IL-8, CCL2, CCL20, CXCL1, CXCL2, and CX3CL1 was significantly induced in HUVECs prior to infection with HTNV (MOI = 1) for 48 h and then exposed to IL-33 (20 ng/ml) for 6 h." (PMID 25658420, 2015). "Indeed, MyD88-deficient mice lack the production of neutrophil chemokines (CXCL1, CXCL2) at the infection site." (PMID 25084278, 2014). "In aggregate, these findings indicate that CCR2 depleter mice produce wild-type levels of CXCL1 and CXCL2 during respiratory fungal infection and display preserved neutrophil recruitment to the site of infection, though these processes per se are insufficient to prevent the development of IA." (PMID 24586155, 2014). "We also measured CXCL1 and CXCL2 levels at the site of infection." (PMID 25084278, 2014). "Consistent with the trend of NF-κB activity, the expression levels of three of the four selected chemokines regulated by NF-κB (Ccl2, Ccl3, Ccl5, but not Cxcl1), peaked on day 32 post-infection." (PMID 25116007, 2014). "Of note, MCMV-infected IL-22R−/− mice did not exhibit heightened virus load, reduced neutrophil recruitment, or CXCL1 protein in peripheral sites of infection (data not shown)." (PMID 24721575, 2014). "Infection activated the JNK pathway and induced secretion of the chemokine KC (CXCL1)." (PMID 24416445, 2014). "Three hours after infection, CXCL1 was slightly increased in both genotypes without significant differences." (PMID 23358433, 2013).
infection (continued). "To further investigate the impact of 14C11 pre-treatment on HRV16-induced allergic airway inflammation we analysed Th2-type cytokine concentrations as well as the neutrophil and eosinophil chemokine attractants CXCL1 in BAL and eotaxin-1 levels in lung homogenate at day 2 after infection." (PMID 23935498, 2013). "The similar expression patterns of CXCL1 and α-SMA later in the infection when fibrotic pathology differs between strains suggests that there may be additional factors involved." (PMID 21666794, 2011). "In support of this hypothesis, we found that Cxcl1 was significantly differentially expressed between A/J and C57BL/6J mice at 2, 6, and 12 hours after infection with S. aureus." (PMID 20824097, 2010). "In the absence of infection, CF-TG cells constitutively exhibited an inflammatory signature, including genes that encode molecules such as IL-1α, IL-β, IL-32, TNFSF14, LIF, CXCL1 and PLAU." (PMID 19399182, 2009). "Enhanced production of CXCL1 was consistent throughout infection, suggesting that this effect may occur independent of differences in Mtb burden." (PMID 40924769, 2025). "However, indicating a broader inflammatory response in the whole brain, transcripts encoding pro-inflammatory cytokines, such as interleukin-1α (IL-1α), interleukin-6 (IL-6), interleukin-8 (IL8/CXCL1), and especially MCP1/CCL2, exhibited significant upregulation at 2- or 4-days post-infection." (PMID 40365287, 2025). "To explore the possibility that elevated CXCL1 levels may occur independent of infection in Ctsz−/− mice, we sacrificed uninfected mice of both sexes." (PMID 40924769, 2025). "Notably, EV-A71 infection led to activation of the C5a–C5aR1 axis in U87-MG cells, and knockdown (siC5aR1) or blockade (PMX53) of C5aR1 significantly suppressed EV-A71-induced astrocyte activation and proinflammatory cytokine (e.g., CXCL1) production." (PMID 39679722, 2025). "Infections with pso variants (especially with the HK2 variant lacking O-Ag biosynthesis) activated endothelial cells with abundant expression of cell adhesion molecules (ICAM-1 and VCAM-1) and inflammatory mediators (CCL2, CXCL1, CXCL8, CCL20, and IL-6)." (PMID 40570043, 2025). "Additionally, severe influenza virus infection was associated with hypercytokinemia, including increased cytokine (IFNβ, TNF, IL-10 and IL-12p70) and chemokine (MCP-1 (CCL2), KC (CXCL1), IP-10 (CXCL10) and RANTES (CCL5)) levels in the severe infection group at 7 dpi." (PMID 41285788, 2025). "On the opposite, the strong stimulatory effect of OMVs on IL-6 and the chemokine CXCL-1 secretions always predominated the suppression induced by infection no matter whether BMMs were infected before or after OMVs treatment." (PMID 38533334, 2024). "However, the secretion of CXCL1 showed no significant different at early time points after infection (12 and 24 h) in Trim26–/–mice." (PMID 38166150, 2024). "However, in addition to IL-12, GRA24 upregulates several other proinflammatory cytokines and chemokines, including IL-6, TNF, MCP-1, CCL5, CXCL1, and CXCL10 that could contribute to the lethal outcome of infection." (PMID 39440975, 2024). "At 3 days post-infection, intravenous administration of hMSCs significantly decreased the concentrations of pro-inflammatory cytokines and chemokines, i.e. TNF-α, IL-1β, MCP-1, CXCL1 in lung homogenate and/or BAL fluid, respectively, as compared with mice treated with NHLFs group." (PMID 37704783, 2023). "CXCL1 secretion was induced by infection of HSAE cells, but not A549 cells." (PMID 37578262, 2023). "Although infection did not influence mRNA expression level of Ifn-β gene inside macrophages cultured on titanium surfaces and titanium with silver or tetracycline, the expression levels of Tnf-α, Cxcl-1 and Il-6 genes significantly increased." (PMID 37929187, 2023). "Furthermore, CXCL1, IP-10 and IL-8 peaked at around four weeks post-infection, even though by this time C. trachomatis was no longer detectable by PCR." (PMID 37862368, 2023).
infection (continued). "Similarly, chemokines (e.g. CXCL1, CXCL2, and CXCL5) that play a pivotal role in neutrophil recruitment to sites of infection and injury were induced 2–3 orders of magnitude, whereas CXCL12/SDF‐1 and adhesion G‐protein coupled receptor F5 (ADGRF5, GPR116) expression was unaffected." (PMID 36151614, 2022). "Moderate and severe infection with Wuhan and Alpha variants of SARS-CoV-2 cause an increase in CXCL1 levels in the blood, while SARS-CoV-2 Delta and Omicron variants do not cause an increase in CXCL1 levels." (PMID 36613652, 2022). "Compared to virulent MERS-CoV-MA-WT and MERS-CoV-MA-mNLS infection, attenuated MERS-CoV-MA-Δ4b induced, either at 4 or 6 dpi, lower levels of CCL2, CCL4 and CXCL10, which are monocyte and macrophage chemoattractants, and CXCL1 and CXCL2, which are neutrophil chemoattractants." (PMID 36129908, 2022). "Moreover, increased serum levels of CXCL1 and CXCL2, as potent chemo-attractants for neutrophils mobilization via their sole receptor CXCR2, can recruit neutrophils from peripheral circulation to the focus of infection." (PMID 36369287, 2022). "Among the selected cytokines or chemokines, IL-6, GM-CSF, CXCL1, CCL2, MIP-1α, MIP-2, IFN-α, and M-CSF (which are involved in acute inflammation and B cell maturation) were highly upregulated, although they exhibited transient inhibition at 1 day post-infection." (PMID 34068322, 2021). "Also, TNF levels in BALF were significantly lower in Lysmcre-Btkfl/Y mice as compared to controls (p<0.05) 3 hours after D39 infection, whereas IL-6, CXCL1 and CXCL2 levels were not altered." (PMID 34552589, 2021). "We speculated that the increase in Cxcl1 levels rather than the decrease in IL-1β levels may account for the more severe infection in the GSDMD−/− mice." (PMID 34011393, 2021). "Our results showed that HTNV infection led to elevated cytokine production, including CXCL-1, CCL-5, IL-6, IL-12, TNF-α, and IFN-γ in Nlrc3−/− mice, and the levels of these cytokines peaked at 6 or 9 dpi; in comparison, WT mice had weaker cytokine responses throughout the infection process." (PMID 34335602, 2021). "In addition, WT cells exhibited similar amounts of IL-1α, IL-1β, and TNF-α release with and without treatment, but lower levels of CXCL1 and IL-6 in infection supernatants." (PMID 33441602, 2021). "As the infection progresses, the expression of CXCL1/2/5 decreases and in turn upregulates the expression of CXCL13 by macrophages, monocytes, and DCs, which contributes to B lymphocyte accumulation in the infected lungs during the late infection and recovery stages." (PMID 34868067, 2021). "To identify mechanistic bases for the different numbers of neutrophils at the site of infection, we measured the main chemokine factors for neutrophil attraction, including the CCR1 ligands CCL3, CCL4, and CCL5 and the CXCR2 ligands MIP-2/CXCL-2, KC/CXCL-1, and CXCL5." (PMID 32424099, 2020). "Interestingly, at day 17 CXCL-1 was also reduced by LDA infection in the CMtb, although not significantly." (PMID 32046344, 2020). "Our results showed that the levels of CXCL1 and MIP-2 quickly reached peak 4 h after infection, and these chemokines may be secreted by macrophages because they were the majority cells in BALF before infection." (PMID 33163539, 2020). "In our data, neutrophil recruitment to infection site, in ethanol-fed mice, was impaired even though we did not observe decrease in both CXCL1 and CXCL2 BALF levels, indicating that ethanol consumption is responsible for compromising neutrophils activation and migration." (PMID 32701055, 2020). "In addition to G-CSF and GM-CSF, the chemokine CXCL1 (KC) was significantly increased in all mice inoculated with AgNPs, regardless of infection status." (PMID 31398832, 2019). "While this indicates that sustained early TNF and CXCL1 are not due to increased bacterial burden at this timepoint, there have been reports of increased or decreased bacterial load in Ifnar1-/- mice in longer term infection models." (PMID 31385572, 2019).
infection (continued). "We further examined the gene expression of pro-inflammatory chemokines (CXCL1, CXCL2 and CCL2), chemokine receptor CCR7, and TLR4 in lung tissues in order to determine the potential mechanism(s) of immune cells infiltration into the lungs of newborns following low dose infection with B. pertussis." (PMID 28798335, 2017). "In addition to G-CSF in MDSC recruitment from bone marrow, other studies have also demonstrated that chemokines CXCL1 and CXCL2 could promote the recruitment of MDSCs to the spleen during infection and inflammation." (PMID 26797765, 2016). "The larger lesions observed in μMT mice were associated with approximately 10-fold greater numbers of bacteria recovered from the lesions 3 d after infection (p < 0.05), as well as higher levels of the inflammatory chemokine CXCL-1 (p < 0.01), but not IL-17A (p = 0.15)." (PMID 26828524, 2016). "The levels of inflammatory cytokines and chemokines, i.e., IL-6, TNF-α, CCL3/MIP-1α, CXCL1/KC, and CXCL10/IP-10, which have been reported to contribute to lung pathology, also decreased in BALF from Mint3−/− mice compared to those from WT mice on day 4 after infection." (PMID 27883071, 2016). "Moreover, by 48 h after infection CXCL1 levels and neutrophil recruitment to the lung is unaffected in CCR2-depleter mice, thus suggesting that distinct mechanisms of neutrophil recruitment are operational at various times after infection." (PMID 25629406, 2015). "Besides CXC chemokines, CXCL1 and CXCL2, the activated components of a complement cascade, e.g. C3a and C5a, were shown to be potent chemoattractants for PMN localization to the sites of infection." (PMID 24651866, 2014). "However, at day 3 post-infection, the Socs4R108X/R108X mice showed significantly higher levels of cytokines and chemokines, such as IL-1β, IL-4, IL-5, IL-6, IL-12p40, IL-13, IFN-γ, and KC (CXCL1), MIP-2 (CXCL2) and MCP-1 (CCL2), respectively." (PMID 24809749, 2014). "We observed that a number of NF-κB inducible genes were significantly elevated at 4 weeks post-infection (but not at 2 weeks) by qRT-PCR in B6 miR-146a−/− joints, compared to WT, including cytokines IL-1β and IL-6, as well as neutrophil chemokines Cxcl1 and Cxcl2." (PMID 24967703, 2014). "In addition, blood samples were collected at 2, 6, 24 and 48 h post-infection to analyse the production of inflammatory cytokines such as TNF-α, IFN-γ, IL-6, keratinocyte chemoattractant (KC or CXCL-1, equivalent to human IL-8) and anti-inflammatory cytokine IL-10." (PMID 24107297, 2013). "To determine if the decrease in CXCL1 at the later stages of infection was due to transcriptional differences in regulation in the absence of lumican, we determined Cxcl1 expression by real time qRT-PCR in total RNA extracted from Lum+/− and Lum−/− infected corneas." (PMID 23358433, 2013). "As neutrophils are massively recruited during PVM infection, chemokine KC (CXCL-1) and MIP-2 (CXCL-2) - two major chemokines involved in neutrophils recruitment in mouse - were measured in the BALF of P2Y2+/+ and P2Y2−/− mice by ELISA at days 8, 9, 10 and 12 post-infection." (PMID 23185614, 2012). "In addition to immunosuppressive molecules, antiviral proteins (such as IFNs) produced during viral infections attenuate initial KC/CXCL-1 and MIP2/CXCL2 responses to secondary pneumococcal challenge, resulting in increased persistence of bacteria and death in mouse models of infection." (PMID 23055935, 2012). "Additionally, whole lungs from anti-Dll1 Ab treated mice at day 7 post-infection had significantly higher protein levels of CCL2 and CXCL1, molecules that play a critical role in the recruitment of monocytes/macrophges and neutrophils into inflammatory lesions." (PMID 22072963, 2011).